CTLA4 (cytotoxic T-lymphocyte associated protein 4)
Diseases named in the same sentence as CTLA4 in open-access papers (continued):
Sharing a sentence is not in itself a finding about the gene and the disease.
tumor (continued). "Furthermore, the research indicated that the autophagy of tumor cells increased the expression of ICI-related immunosuppressive molecules (e.g., PD-1 and CTLA-4) and affected anti-tumor immune responses directly." (PMID 34956321, 2021). "Moreover, the combination of MTP-HDL with either anti-PD-1, anti-CTLA-4, or both anti-PD-1 + anti-CTLA-4 ICB further enhanced the anti-tumor effect of MTP-HDL therapy." (PMID 33924237, 2021). "By contrast when we administered anti-PD-1 later, at the peak of SPAS-1+ T cell expansion invoked by IRE plus anti-CTLA-4, we observed sustained control of tumor growth, particularly in those mice that did not respond fully to initial dual therapy." (PMID 34162858, 2021). "In the last decade, programmed death protein-1/programmed death-ligand-1 (PD-1/PD-L1) and cytotoxic T lymphocyte antigen 4 (CTLA-4) have become two of the most important pathways targeted by ICI and are involved in the induction and maintenance of immunotolerance within the tumor microenvironment." (PMID 34359249, 2021). "Thus, this chimeric CTLA4-CAR can enhance the antitumor activity of CAR T cells and shed light on the strategy of using armed CAR T cells to target the immunomodulatory tumor microenvironment." (PMID 33868277, 2021). "Contact-dependent mechanisms utilizing CTLA-4, lymphocyte-activation gene 3 (LAG-3), and T cell immunoglobulin and ITIM domain (TIGIT) prevent activation and maturation of dendritic cells (DCs) thus preventing an effective anti-tumor T cell response." (PMID 34177968, 2021). "For tumor patients who are not sensitive to anti-CTLA-4 and anti-PD-1/PD-L1 treatment, scRNA-seq can be used to analyze specific tumor tissues and tumor cells and discover the mechanism of drug resistance." (PMID 33648534, 2021). "In conditions in which anti–PD-1 alone or in combination with anti–CTLA-4 failed to reduce tumor growth in mice receiving a standard diet, KD, or oral supplementation of 3HB reestablished therapeutic responses." (PMID 33320838, 2021). "In comparison to PD-1 and CTLA-4 checkpoints, the mechanism of B7-H3 (CD276) in suppressing tumour development still remains unclear." (PMID 33995529, 2021). "Their tumor-permissive effect is achieved either by restraining the proliferation of tumor-specific effector cells or by limiting the secretion of IL-2 and IFN-γ owing to the expression of CTLA-4, glucocorticoid-induced tumor necrosis factor receptor (GITR), and Foxp3." (PMID 34831048, 2021). "Checkpoint proteins such as CTLA-4, PD-1, LAG-3, TIM-3, VISTA and TIGIT are mostly found on the surface of T-cells, with some also found on dendritic cells (DCs) and monocyte/macrophages (PD-L1, TIM-3, LAG-3, VISTA) or tumour cells (PD-L1, TIM-3)." (PMID 33923305, 2021). "Furthermore, the addition of anti-CTLA-4 antibodies enhanced mRNA vaccine-induced cytotoxicity, CD8+ T cell tumor infiltration, and long-term reduction in tumor growth." (PMID 33670942, 2021). "Cytotoxic T Lymphocyte antigen 4 (CTLA-4), Programmed Cell Death 1 (PD-1), and Programmed Cell Death Ligand 1 (PD-L1, also known as B7-H1 or CD274) pathways are the best known immune checkpoint pathways for immune responses within the tumor microenvironment." (PMID 33823818, 2021). "Therefore, blocking the functional molecules expressed on Tregs such as CTLA-4, PD-1, CCR4, TGF-β, Foxp3, or completely eliminating the presence of Tregs can improve the immune escape effect of tumor inflammatory microenvironment." (PMID 34062992, 2021). "However, the tumor cells will express immune checkpoint biomarkers such as PDL1 and CTLA4 to suppress T cell responses and lead to T cell exhaustion." (PMID 34512816, 2021). "Notably, elevated expression of LAG-3 by tumor-infiltrating lymphocytes in PDAC patients was previously detected along with increased PD-1 and CTLA-4 expression." (PMID 33803936, 2021).
tumor (continued). "We also did not investigate other immune-oncologic biomarkers such as CTLA-4 and the expressions of other immune checkpoints in tumor and immune cells." (PMID 35070953, 2021). "This is in line with the results of a study reporting on matched pre and on-treatment tumor biopsies from patients under anti-CTLA-4 revealing no change in Ki-67 expression in post-treatment TILs having expanded under therapy." (PMID 33602280, 2021). "CTLA-4 inhibitors prevent CTLA-4 from binding to CD80 and CD86, thereby initiating signal 2, which can activate specific T cells in lymphoid organs and promote their migration into the tumor." (PMID 33854960, 2021). "Specifically, TCL6 was positively correlated with tumor infiltration with immune cells, including CD8+ and CD4+ T lymphocytes, neutrophils, B and DCs, as well as with the expression of PD-1, PD-L1, PD-L2 and CTLA-4 immune checkpoint molecules." (PMID 34943820, 2021). "The study was designed to optimize the condition for producing an effective dendritic cell (DCs) based immunotherapy by using DCs and T lymphocytes together with tumor-infiltrating lymphocytes (TILs) and tumor-infiltrating DCs (TIDCs), treated with anti-PD1 and anti-CTLA4 monoclonal antibodies." (PMID 37305162, 2021). "Whereas, according to recent studies, tumor cells can avoid the immune response by utilizing various immune checkpoints, which can play a crucial part in cancer immunotherapy, including programmed death-1 (PD1), PDL1, and CTLA4." (PMID 34603443, 2021). "It has previously been shown that in vivo treatment of MOC2 tumors in a murine HNSCC model with PD-1 and CTLA-4 blockade does not confer increased anti-tumor immunity or increased presence of CD8+ tumor-infiltrating lymphocytes." (PMID 33668795, 2021). "CTLA-4 expression is increased in HNSCC tumor samples compared to normal tissue and is not correlated with LN metastasis or pathological tumor grade." (PMID 33804419, 2021). "Specifically, we tested whether IRE in combination with anti-CTLA-4 would promote SPAS-1+ CD8+ T cell expansion and regression of residual primary tumor growth in the TRAMP-C2 model." (PMID 34162858, 2021). "These genes were defined as the tumor reactive signature (TRS), including co-inhibitory receptors (CTLA4, PDCD1, TIGIT and HAVCR2), reactive markers (CD38 and ENTPD1), effector molecules (NKG7 and PRF1), tumor necrosis factor TNFRSF9 and critical exhaustion-related regulator TOX." (PMID 34804045, 2021). "Sham treatment followed by anti-CTLA-4 (Sham + anti-CTLA-4) generally failed to impede tumor growth, as continued tumor growth was observed in more than half (53%; 7/13) of mice with this treatment arm." (PMID 34162858, 2021). "As CTLA-4 has a stronger binding affinity for B7 ligands than does CD28, CTLA-4 competitively inhibits the ligation of B7 and CD28, thereby attenuating T cell proliferation and activation, and suppressing anti-tumor immunity." (PMID 34541363, 2021). "In addition, the interaction of tumour cells with CAR T cells can induce the expression of immunosuppressive molecules, such as CTLA-4, EOMES and PD1, leading to T-cell exhaustion or dysfunction." (PMID 33462245, 2021). "Thus, tumor-infiltrating T cells have been the early focus for understanding the mechanisms of ICB, since they are direct targets of anti-PD-1 or anti-CTLA-4." (PMID 34000441, 2021). "Tumour-infiltrating CD8+ T cell frequencies were mostly unaffected, although intratumoural CD8+ T cell frequencies increased between mice treated with single-agent anti-CTLA-4 and mice treated with combination checkpoint blockade." (PMID 34784792, 2021). "The antitumor action capacity of CTLA-4 blocking monoclonal antibodies was first evaluated preclinically and subsequently validated, even if they have no tumor specificity." (PMID 34638281, 2021).
tumor (continued). "In another experiment, a 20 Gy dose of radiation was used in combination with an anti-CTLA-4 antibody, which resulted in tumor reduction at the irradiation site, but no abscopal effect on metastatic lesions was observed." (PMID 33799560, 2021). "Similar to the treatment with AICAR and anti-CTLA-4 antibody, the combination therapy with AICAR and anti-PD-1 antibody significantly reduced tumor growth due to increased anti-tumor T cell activity in comparison with AICAR monotherapy or anti-PD-1 antibody treatment alone." (PMID 34649584, 2021). "To this end, we tested six strains with different characteristics with PD-1 antibody and CFA and successive experiments with anti-CTLA-4 with anti-PD-1, in the presence or absence of tumor antigen." (PMID 33571254, 2021). "In contrast, in a breast tumor model, an increase in CD8+ T cell motility by CTLA-4 blockade did not promote tumor killing, whereas a combination with radiotherapy decreased CD8+ T cell motility and enhanced tumor injury." (PMID 34572844, 2021). "During the interaction between antigen-presenting cells and T cells, CTLA-4, which functioned as a negative T-cell activation modulator in lymphoid tissues, is up-regulated on T cells due to the binding of tumor antigens to T-cell receptors." (PMID 34804979, 2021). "Moreover, serum LDHA levels are related to burthen of tumor and poor clinical outcomes to immune checkpoint (such as PD1 and CTLA4) blockade therapy." (PMID 34852326, 2021). "As the tumor cells expressed high PDL-1 and CTLA4 the syngeneic OSCC13 grafting model may be amenable for targeting immune checkpoints in particular in combination with radiotherapy as we have shown that OSCC13 cells and tumors are radiosensitive." (PMID 34290694, 2021). "The presence of few CTLA-4 positive cells within the tumor microenvironment in the context of a negativity of tumor cells seems to indicate that this pathway is not particularly involved in the immunoescape of epSCCs." (PMID 34359249, 2021). "To eliminate confounding effects of diet and determine whether outcomes could be improved in DIO mice, we evaluated AdT/CpG combined with anti-CTLA-4 in diet-matched, obese-resistant (OB-RES) versus DIO tumor-bearing mice." (PMID 34064933, 2021). "By contrast, we noted that despite similar proportions of circulating tumor-specific memory CD8+ T cells at later time points, mice that received monotherapy anti-CTLA-4 failed to control a recurrent tumor challenge." (PMID 34162858, 2021). "Moreover, we found an improved therapeutic effect when YUMM tumor-bearing mice were treated with TA99 combined with MEKi and immune checkpoint blockade (anti-PD1 and anti-CTLA4)." (PMID 33520112, 2021). "Moreover, it is generally accepted that the high expression of immune checkpoints such as CTLA4, PD-1, BTLA, CD274, and LAG3 will benefit tumor cells to escape immune surveillance, avoid immune-mediated apoptosis, and finally lead to poor prognosis." (PMID 34745259, 2021). "The binding of CTLA4 to its ligands CD80 and CD86 leads to tumor cell immunosuppression." (PMID 34143198, 2021). "PD1/PD-L1, CTLA-4, and TIM-3 are critical immune checkpoints responsible for tumor immune escape." (PMID 34956895, 2021). "They further demonstrated that CD80 is necessary for the tumor-initiating stem cells to endure immune attack and CD80 could dampen the activity of cytotoxic T cells through directly engaging with CTLA4." (PMID 34722635, 2021). "On average, mice that received BEMPEG and anti-CTLA-4 treatments had fewer lung metastases, regardless of local treatment to the tumor." (PMID 33937052, 2021). "Consequently, treatment of cancer patients with PD-1/PD-L1 and CTLA-4 ICIs can relieve this tumour-intrinsic suppression and allow cytotoxic CD8 T-lymphocytes to re-enter the tumour and clear the tumour cells." (PMID 35052732, 2021).
tumor (continued). "Analysis of pre-treatment TCR clonality in metastatic melanoma patients suggested that T-cell clonality within the tumor did not predict response to CTLA4 blockade." (PMID 34899700, 2021). "The inhibitory chimeric antigen receptors contain a PD-1 or CTLA-4 based inhibitory domain, which could shield the normal cells from being killed by specific CAR-T cells, to overcome the on target, off tumor toxicities." (PMID 34858843, 2021). "The anti-CTLA-4 monoclonal antibody directed against the inhibitory receptor exempts the inhibitory effect of CTLA-4 activation, resulting in activation of T lymphocytes and thus the destruction of tumor cells." (PMID 33925915, 2021). "Programmed death-ligand 1 (PD-L1) and cytotoxic T-lymphocyte associated protein 4 (CTLA4) were similarly expressed between tumor and normal brain tissue (i.e., not overexpressed in tumor)." (PMID 33431066, 2021). "Also, cells in TME interact with each other and with the neoplastic cells through different suppressor receptors like PD-1, CTLA-4, CD70 and gangliosides that increase the tumour immune escaping." (PMID 33804731, 2021). "Pardoll's study demonstrated that anti-PD-1 targeting tumor infiltrating lymphocytes (TIL) can complement the anti-tumor activity of anti-CTLA-4 through non-redundant pathways." (PMID 33391454, 2021). "By blocking these negative immune checkpoints, ICBs (anti-CTLA-4 and anti-PD-1/L1) re-invigorate the patients’ endogenous immune cells, particularly T cells to ward off tumor." (PMID 34830176, 2021). "Anti-PD-1 and anti-CTLA-4, delivered alone or in combination, did not induce tumour regression or improve mouse survival." (PMID 34784792, 2021). "Compared with normal control tissues, the expression level of CTLA4 in tumor tissues was not significantly different." (PMID 34218795, 2021). "In both LL/2 and LL/2-tdTomato/Luc tumor models, neither anti-PD-1 nor anti-CTLA-4 mAb reduced the tumor size although mice challenged with LL/2-tdTomato/Luc cells had significantly smaller tumors compared to mice challenged with LL/2 cells." (PMID 34411144, 2021). "Similar to ICIs targeting PD-1 and PD-L1, the CTLA-4 Ab alone did not significantly affect tumor growth." (PMID 34461854, 2021). "However, when we tested combination treatment with TA99 and either anti-CTLA4 or anti-PD1, we observed a significant reduction in tumor growth compared to control animals or those that received monotherapy." (PMID 33520112, 2021). "At baseline, there was no notable difference of CTLA-4 expressing Tregs in the tumor-bearing mice between the two models." (PMID 34774008, 2021). "In our study, application of IRE prior to anti-CTLA-4 therapy promoted profound changes in the neoantigen-specific T cell response, resulting in increased numbers of SPAS-1+ T cells systemically in the spleen and concentrated in the tumor and distant sites." (PMID 34162858, 2021). "CTLA-4 blocks the binding of antibodies to CTLA-4 expressed on T lymphocytes, leading to the beneficial expansion of effector T cells that recognize tumor antigens and eliminate tumors, thereby inhibiting tumor growth." (PMID 34447484, 2021). "Of note, TMDD does not apply to anti-CTLA4 or anti-PD1 mAbs since target engagement is not related to the tumor burden but rather to the immune system." (PMID 34451893, 2021). "There was also no impact of anti-PD-1, anti-PD-L1, or anti-CTLA-4 ICI therapy on the frequency of CD8+ SPAS-1+ T cells in tumor following any of the ICI therapy regimens." (PMID 34162858, 2021). "Correlating with the sensitivity of both models to anti-CTLA-4 treatment, no notable differences were observed in the frequencies of CTLA-4 expressing Tregs between two tumor types." (PMID 34774008, 2021). "Addition of anti-PD-1 following dual IRE + anti-CTLA-4 treatment blocks tumor growth in non-responsive cases." (PMID 34162858, 2021).
tumor (continued). "A combined PD‐1/CTLA‐4 blockade dramatically (∼14‐fold) increased the trafficking of CD8+ T cells to the brain mainly through the upregulation of T cell entry receptors intercellular adhesion molecule 1 and vascular adhesion molecule 1 on tumor vasculature." (PMID 34145792, 2021). "Tumor cells evade immune detection by exploiting vulnerabilities in the multistep process of T cell activation at various stages, including downregulating MHC class I antigen presentation, expressing CTLA4, or upregulating PD-L1 expression." (PMID 33564739, 2021). "The mechanism of this phenomenon is still unrecognized, although in mouse models lacking CD4+ or CD8+ T cells the anti-CTLA-4 and anti-PD-1 treatment promoted normalization of tumor vessels via Th1 CD4+ helper T cell activation." (PMID 34439305, 2021). "ICI used against CTLA-4 can block these negative signals and enhance vaccine-induced tumor-specific CTL functions." (PMID 34960142, 2021). "While IL-10 production was detected in a relatively small proportion of the CD8+CD103+ cells, it suggested a possible upregulation of an immunosuppressive phenotype by tumor-infiltrating CD103+ TRM, therefore expression of the inhibitory markers CD39, CTLA-4 and PD-1 was investigated." (PMID 33479027, 2021). "In consistent with our mechanistic findings, immunofluorescence and flow cytometric analysis showed that mono‐Sunitinib or Sunitinib plus CTLA‐4 mAb treatment significantly decreased PD‐L1 level, increased CD8+ CTL population, and enhanced their activity in the tumor region of immune competent mice." (PMID 33510997, 2021). "The depletion of Treg at tumor sites and increase of peripheral CD8+ T effector cells have been hypothesized to drive irAEs, induced by CTLA-4 blocking antibodies." (PMID 34790123, 2021). "Their respective findings that CTLA-4 and PD1 immune checkpoints inhibit the activity of cytotoxic T-cells and allow tumours to grow, led to the design of inhibitors against these molecules with the goal to enhance T-cell-mediated cell death of tumour cells." (PMID 34298736, 2021). "We observed that monotherapy with ICI antibodies targeting PD-1, PD-L1, and CTLA-4 failed to impede tumor growth when applied to tumor-bearing mice." (PMID 34162858, 2021). "We hypothesized that immunotherapy with anti-CTLA-4 and bempegaldesleukin (BEMPEG; NKTR-214), a CD122-preferential IL2 pathway agonist, after primary tumor RT or resection would reduce metastases in a syngeneic murine NSCLC model." (PMID 33937052, 2021). "Finally, IDO inhibitors increased the survival of tumor-carrying mice when combined with anti-PD-1/anti-CTLA-4 antibodies, through the reduction in Treg in the TME and the increase in anti-tumor effector cells." (PMID 33920505, 2021). "Targeting of CTLA-4 during priming indeed induces a circulating CD8+ TEM phenotype but also results in increased CD8+ TRM cells, leading to enhanced protection in subcutaneous tumor models." (PMID 33467606, 2021). "In recent studies, CTLA-4 expression has been reported also on non-immune cells such as tumor cells, where it has been supposed to play a role in survival, by promoting proliferation or inducing apoptosis." (PMID 34201082, 2021). "Tregs, in a CTLA-4-dependent manner, inhibit proliferation of CD4+ and CD8+ T cells and downregulate the expression of co-stimulatory molecules (CD80 and CD86) on DCs, attenuating their capacity for induction of effective anti-tumour immunity." (PMID 34299373, 2021). "Tumor cells mediate immunosuppression taking over inhibitory checkpoint proteins such as PD-1, T cell immunoglobulin and mucin domain 3 (TIM-3), lymphocyte activation gene 3 (LAG-3), and CTLA-4 expressed on the surface of T lymphocytes." (PMID 34575678, 2021).